ELDR (EGFR long non-coding downstream RNA)
Synonyms: Fabl; formerly LINC01156
Gene: Long non-coding RNA gene on chromosome 7 (55,235,965 to 55,255,675, reverse strand). Ensembl gene ENSG00000280890.
Diseases named in the same sentence as ELDR in open-access papers:
ELDR is named in the same sentence as 6 diseases in open-access papers, as found by Europe PMC text mining. Sharing a sentence is not in itself a finding about the gene and the disease. The quoted sentences say what the papers report.
glioma (2 papers, 2021 to 2025). A benign or malignant brain and spinal cord tumor that arises from glial cells (astrocytes, oligodendrocytes, ependymal cells). "ELDR expression is significantly upregulated in GBM in relation to normal brain and low-grade gliomas (LGG) and is positively correlated with EGFR gene copy number and RNA transcript levels in GBM." (PMID 40678238, 2025). "In glioma grade IV, highly activated DEGs included STOM, IGHG4, CXCL13, MMP13, and CAPN6, while highly downregulated DEGs included JAZF1-AS1 and ELDR." (PMID 33948562, 2021).
bladder cancer (1 paper, 2025). "This suggests that TRIM44 overexpression caused by ELDR probably acts in bladder cancer by making this essential cancer-causing pathway work too hard." (PMID 41357604, 2025). "Collectively, these findings delineate the ELDR/miR-1343-3p/TRIM44 axis as a functionally independent pathway that expands the known regulatory network of lncRNAs in bladder cancer pathogenesis." (PMID 41357604, 2025).
oral cancers (1 paper, 2022). "The ELDR is highly expressed in oral cancer samples compared to normal cells and induces cell proliferation by increasing EGFR and ILF3/cyclin E1 signaling." (PMID 35378133, 2022). "It will be important to know how ELDR is upregulated in oral cancer and probably in other cancers." (PMID 35378133, 2022). "We recently reported a potential oncogenic role of ELDR in oral cancer." (PMID 35378133, 2022). "It is plausible that ELDR differentially regulates cell cycle in NOKs and oral cancer cells." (PMID 35378133, 2022). "This indicates that ELDR may be one of the potential drivers in oral cancer which is responsible for tumorigenic transformation." (PMID 35378133, 2022). "The lncRNA ELDR (EGFR long noncoding downstream RNA) was recently shown to be highly expressed in oral cancers as compared to adjacent nontumor tissue, and we previously reported that ELDR may be an oncogene as inhibition of ELDR reduces tumor growth in oral cancer models." (PMID 35378133, 2022).
cancer (4 papers, 2022 to 2025). A tumor composed of atypical neoplastic, often pleomorphic cells that invade other tissues. "Despite its association with various cancers, the role of lncRNA ELDR in BCa remains unclear." (PMID 41357604, 2025). "Last, expression of ELDR correlates with overall survival of GBM and is markedly elevated in GBM compared to other cancers in TCGA datasets." (PMID 40678238, 2025).
tumor (3 papers, 2022 to 2025). "We found that the expression level of ELDR was obviously upregulated in BCa tissues compared to the paired adjacent normal tissues, correlating with tumor size, invasion depth, TNM stage and poor prognosis in BCa patients." (PMID 41357604, 2025). "Functional experiments demonstrate that ELDR enhances BCa cell proliferation, colony formation, migration, and invasion in vitro and accelerates tumor growth in vivo." (PMID 41357604, 2025). "Mechanistically, ELDR functions as a competitive endogenous RNA (ceRNA) by sequestering tumor-suppressive miR-1343-3p in the cytoplasm, which consequently leads to the upregulation of the oncogene TRIM44." (PMID 41357604, 2025). "In conclusion, tumor promoting lncRNA ELDR has potential role in induction of proliferation in NOKs by increasing G2/M transition of cell cycle when the ELDR is overexpressed." (PMID 35378133, 2022). "Collectively, these results demonstrate that ELDR inhibition could suppress BCa tumor growth in vivo." (PMID 41357604, 2025). "Interestingly, targeted inhibition of ELDR could inhibit in vivo tumor growth in a mouse model." (PMID 37568568, 2023).
ELDR also shares sentences with these, for which no sentence is quoted: ovarian carcinoma (1 paper).